MMP13 (matrix metallopeptidase 13)
Diseases named in the same sentence as MMP13 in open-access papers (continued):
Sharing a sentence is not in itself a finding about the gene and the disease.
tumor (continued). "Dark lanes show that the band of 115 kDa indicated the occurrence of MMP-13 in higher mass complexes in both normal tissues and tumor samples." (PMID 36231910, 2022). "Together, these studies indicate that overexpression of MMP-13 in cancer, either by tumour cells or stromal cells in the tumour microenvironment, makes important contributions to tumour growth." (PMID 35805035, 2022). "In all cases, MMP-13 expression was higher in the stroma (fibroblasts and inflammatory cells) compared to tumor cells." (PMID 34204372, 2021). "The study pinpointed that MMP-13 expression is upregulated by IL-1alpha and, to a lesser extent, by phorbol myristate acetate, a tumor promoter, and by tumor necrosis factor alpha." (PMID 34204372, 2021). "MMP13 in EV cargo from NPC was found to up-regulate EMT in tumor cells by increasing the levels of MMP13 in surrounding human umbilical vein endothelial cells and stromal human skin fibroblast cells." (PMID 34943937, 2021). "Similar results were obtained in a glioma patient study indicating its potential use as a predictive biomarker for RT, while another study determined MMP-13 as prognostic marker for tumor aggressiveness and recurrence in head and neck cancer patients." (PMID 34055644, 2021). "Both MMP9 and MMP13 have been shown to release active growth factors such as VEGF from the ECM to increase tumor angiogenesis." (PMID 33808627, 2021). "High levels of MMP-13 expression correlated with tumor stage and distant metastases only in cancer cells (p < 0.001 and p < 0.002, respectively)." (PMID 34452576, 2021). "In the furthermore bioinformatics analysis, we found that MMP1, MMP3, MMP7, MMP9, MMP12, MMP13 all increased in the tumor as compared with the normal esophageal tissues." (PMID 34559117, 2021). "Increased number of involved lymph nodes, metastasis and, as a result, later stage of tumor in patients with high level of MMP-13 expression suggests that MMP-13 probably plays a role in promoting tumor invasion and metastasis." (PMID 34452576, 2021). "MMP1, MMP3, MMP7, MMP12, and MMP13 belong to the matrix metalloproteinase family, and MMPs were able to participate in the tumor metastasis process by degrading the ECM." (PMID 34381520, 2021). "Gene expression analysis of PIP-expressing 4T1 cells (4T1-PIP) revealed that genes associated with tumor metastasis such as CCL7, MMP3 and MMP13, were significantly upregulated in 4T1-PIP cells when compared to the empty vector control (4T1-EV) cells." (PMID 33777801, 2021). "AIM2 knockout in cSCC cells led to decreased expression of invasive proteases MMP1 and MMP13, thereby weakening the invasion of tumor cells." (PMID 34104103, 2021). "In oral squamous cell carcinoma patients, the MMP-13 expression levels highly correlated with different clinicopathological parameters, such as staging and grading of the tumor." (PMID 34055644, 2021). "Meanwhile, down-regulating the expression of MMP2, MMP9 aand MMP13 can reduce tumor cell growth, proliferation and metastasis." (PMID 34820358, 2021). "Based on the TCGA and GTEx data, we found that MMP1, MMP3, MMP7, MMP9, MMP12, MMP13 all increased in the tumor as compared with the normal esophageal tissues." (PMID 34559117, 2021). "As previously acknowledged, MMP-13 can be regarded as a marker of malignant transformation in keratinocytes and has a role in tumor invasion by degrading ECM." (PMID 34204372, 2021). "MMP-13 expression was directly correlated with distant metastasis and tumor stage in epithelial tumoral cells and was inversely correlated with progesterone expression in both tumoral and stromal cells." (PMID 34452576, 2021). "It has been reported that Mmp10 and Mmp13 are highly expressed in tumor cells in cSCC37,38, and almost universally upregulated across all cancers by TCGA database analysis." (PMID 33664254, 2021). "MMP‐13 was described to be overexpressed at the tumor‐bone interface and abrogation of MMP‐13 in this area inhibited bone metastasis." (PMID 33629769, 2021).
tumor (continued). "Our study in vivo highlights the importance of LY3039478 treatment as it inhibits not only the DLL4/Notch signaling but also the levels of MMP13, which promotes growth and tumor progression by degradation of the ECM." (PMID 32042099, 2020). "The role of the miR-125b as a tumor suppressor by targeting the 3′UTR of Matrix Metallopeptidase 13 (MMP13) is already well-known, together with its down-regulation in CSCC compared to healthy skin." (PMID 32911687, 2020). "MMP13 mRNA up-regulation is correlated with tumor size, tumor invasiveness, and lymph node metastasis[40 ▶,41 ▶]." (PMID 32429645, 2020). "MMP-13 has a very important function in tumor invasion and metastasis in most malignancies by degrading type II collagen." (PMID 32429645, 2020). "The importance of the NOTCH1/HES1/DLL4/VEGFA/MMP13 axis in cholangiocarcinogenesis was confirmed in a collection of human iCCA tumor patients, paving the path for further investigations into the role of these genes in this tumor type." (PMID 32042099, 2020). "MMP-13 also plays a regulatory and potent role in wound healing, angiogenesis, inflammation, and tumor progression in many normal and pathological processes." (PMID 32322412, 2020). "MMP13 inhibition can suppress migration, invasion, and tumor formation induced by ETV4 transcription factor in mouse mammary tumorigenic cells." (PMID 33287358, 2020). "Proteomic analyses revealed that OSCC-derived EVs contain a series of tumor-associated proteins, including TRAP1, EGFR, HSP-90, and MMP-13." (PMID 30954079, 2019). "Functional analysis also showed the tumor suppressive role of miR-125b by inhibiting matrix metallopeptidase 13 (MMP13)." (PMID 30682201, 2019). "On the other hand, the M2 macrophage phenotype gene, Arg1, and two pro-angiogenesis/tumor genes (Cxcl14 and Mmp13) were identified as poor prognosis markers." (PMID 31507609, 2019). "MMP-13 plays an important role in the matrix degradation process, which has been confirmed to promote tumour invasion, migration, and angiogenesis in a variety of tumours." (PMID 31413262, 2019). "Knockdown of HPSE is accompanied by downregulation of MMP1, MMP7, MMP10, and MMP13, all of which are directly involved in the degradation of extracellular matrix and facilitate tumor cell invasion." (PMID 31001480, 2019). "In conclusion, we provided evidence that hypoxia increased the MMP-13 levels in tumor-derived exosomes in a HIF-1α-dependent manner." (PMID 29515112, 2018). "For instance, CAF-secreted matrix metalloproteinase-13 (MMP-13) enhanced tumor cells invasion through proteolytic cleavage of matrix-bound VEGF and angiogenesis." (PMID 30103384, 2018). "MMP-13 is an important type of MMPs that is often over-expressed in various tumors and participates in tumor metastases." (PMID 29515112, 2018). "Although MMP-13 slightly promoted tumor invasion, MMP-13 is involved in tumor angiogenesis via activation of focal adhesion kinase (FAK) and extracellular signal-regulated kinase (ERK)." (PMID 29758011, 2018). "We provided evidence that hypoxia increased the MMP-13 levels in tumor-derived exosomes in a HIF-1α-dependent manner." (PMID 29515112, 2018). "We also confirmed by qPCR that a subset of these genes (Anxa10, Ctse, Mmp10, Mmp13, Lcp1) were consistently upregulated in shG9a tumor cells compared to controls." (PMID 30455465, 2018). "Even though numerous studies suggested the importance of MMP13 in tumor progression and metastasis development, by describing its up- or downregulation, very few of them analyzed the impact of these modulations." (PMID 29996935, 2018). "The prognostic significance of the lymph node status (P = 0.000016), macroscopic tumor size (P = 0.0028), and combined MMP13 and ETV4 mRNA level was maintained." (PMID 29996935, 2018). "In vivo experiments revealed that VM was decreased when the number of endothelium‐dependent vessels (EDVs) increased during xenograft tumour growth, whereas MMP‐13 expression was progressively increased." (PMID 28766880, 2017).
tumor (continued). "Extracellular S100A4 stimulates the production of MMP13 in endothelial cells and promotes tumor angiogenesis by the induced secretion of pro-inflammatory cytokines in tumor cells in the tumor microenvironment." (PMID 29069865, 2017). "Western blotting analyses of tumor samples obtained from untreated mice indicated that tumors originating from MCF7‐NRGα2c‐Luc cells expressed MMP13, pSFKs, and pERK1/2." (PMID 29032615, 2017). "In MMP‐13‐overexpressing xenografts, the number of VM channels was extremely low, and the tumour growth rate was significantly decreased." (PMID 28766880, 2017). "MMP2, MMP9, and MMP13 are the main members of the MMPs family and had been reported to play a key role in tumor migration and remote metastasis in HCC and other cancers." (PMID 28959024, 2017). "Recombinant MMP-13 also promotes the secretion of VEGF-A from fibroblasts and endothelial cells, and MMP-13 was suggested to directly and indirectly promote tumor invasion and angiogenesis, both in vitro and in vivo." (PMID 28068383, 2017). "As expected, MMP13 was highly expressed in tumor samples compared to normal samples (69.8% versus 30.2%, P < 0.001)." (PMID 27356745, 2016). "To investigate the potential molecular mechanism involving CCR4-induced cells invasiveness, we profiled differentially expressed metastasis-related genes with a Tumor Metastasis PCR array.and identified MMP13 as a candidate target." (PMID 27356745, 2016). "Both MMP-1 and MMP-13 are able to cleave native fibrillar collagen, an important step in tumor invasion and metastasis." (PMID 27271600, 2016). "MMP-13 is an important mediator of cell-tumor communications by processing soluble factors, such as RANKL, which in turn stimulate osteoclastogenesis." (PMID 27765913, 2016). "In the present study, expression level of MMP13 was found to be decreased under condition of CCR4 knockdown, while overexpression of CCR4 increased the level of MMP13 in tumor cells." (PMID 27356745, 2016). "In cSCC, MMP-13 colocates with laminin-5 to the edge of lesion and subsequently degrades nearby tissue, allowing tumor invasion." (PMID 27293916, 2016). "When treated with small chemical inhibitors against key factors of pathways (U0126 and LY294002), we found that MMP13 expression was inhibited by the blockaded of ERK signaling in tumor cells." (PMID 27356745, 2016). "To test the importance of tumor cell derived MMP13 on establishment of metastasis to the liver, we utilized the splenic injection model to deliver 2.5 × 105Mmp13 knockdown or control MC38 cell lines into wildtype C57bl/6 mice." (PMID 25880591, 2015). "To assess the role of tumor derived MMP13 on the ability of tumor cells to metastasize to the liver, we developed MMP13 stable knockdown cell lines using RNA interference." (PMID 25880591, 2015). "It is well known that MMP1 and MMP13 are strongly related to tumor invasion and metastatic abilities." (PMID 26305549, 2015). "Here, we evaluated the role of both stromal and tumor cell derived MMP13 on the establishment of metastases in the liver." (PMID 25880591, 2015). "Several studies also link elevated levels of MMP13 in either the stroma or tumor cells with cancer progression, however there are reports that alternately suggest a protective role for MMP13." (PMID 25880591, 2015). "Knockdown of Mmp13 utilizing lentiviral shRNA resulted in a decreased ability of tumor cells to migrate and invade in vitro and correspondingly led to the development of fewer metastasis in vivo." (PMID 25880591, 2015). "Several genes showed progressive increases during tumor growth, including Mmp2, Mmp3, Mmp13 and Mmp16, whereas Timp2 and Mmp27 showed more dynamic fluctuations in expression." (PMID 25848906, 2015). "This study demonstrates that stromal as well as tumor derived MMP13 contribute to tumor cell extravasation and establishment of metastases in the liver microenvironment." (PMID 25880591, 2015).
tumor (continued). "The MMP-13 staining index for tumor cells was zero in the 2 AAHs and low in the 2 AISs, while it was high in 9 out of 11 MIAs and in 15 out of the 16 invasive lesions." (PMID 26193700, 2015). "Coupled together, both tumor cell and host derived MMP13 promote the establishment of metastases in the liver." (PMID 25880591, 2015). "MTT, migration and invasion assays were performed to evaluate the role of tumor derived MMP13 on hallmarks of cancer in vitro." (PMID 25880591, 2015). "In agreement with the in vitro studies, expression of MMP13 was sufficient to restore the decreased number of cancer cells in the tumor-draining lymph nodes." (PMID 26308852, 2015). "The effects of CLU knockdown on levels of MMP13 and p-Akt in orthotopic xenograft tumor tissues were also examined by immunochemistry analysis." (PMID 25609201, 2015). "The overall average mRNA expression levels of Mmp3, Mmp10, and Mmp13 were higher in tumor than that in normal tissues (left)." (PMID 25742789, 2015). "Overall, the tumor burden and incidence of metastases decreased in the mice injected with Mmp13 knockdown cells compared to control cells." (PMID 25880591, 2015). "Our data suggest that host MMP-13 is responsible for blood vessel formation and infiltration into tumor mass." (PMID 24581230, 2014). "Concomitantly, the CD31, MMP13 and TGF-β1 enriched micro-environment in the tumor was associated with higher recurrence and distal lung metastasis risks." (PMID 24581230, 2014). "Copy number alterations, mRNA, and protein expression level of MMP13 were compared between tumor and normal tissues using the Mann-Whitney U test." (PMID 25401159, 2014). "The serum level of MMP2 and MMP9 were both up-regulated under MT treatment under the mechanical damage indicated the highly migration ability of tumor cells while MMP13 also showed the enhanced trend." (PMID 24804772, 2014). "MMP-13 also plays an important role in tumor angiogenesis and is involved in other signaling cascades leading to cancer progression." (PMID 24599080, 2014). "We also evaluated Pit-1 overexpression with MMP-1 and MMP-13 knockdown in a severe combined immunodeficiency (SCID) mouse tumor xenograft model." (PMID 25527274, 2014). "Our data indicated that knockdown of MMP-1 and MMP-13 reduced tumor growth in Pit-1-overexpressing mice." (PMID 25527274, 2014). "Our data revealed an obvious correlation between immunoreactivity for MMP-13 and tumour progression only for strong staining, which decreased, and for minimal staining, which increased." (PMID 26019601, 2014). "Of these, overexpression of MMP13 which is a collagenase appeared to be contributing to tumor cell invasion, metastasis, and poor prognosis." (PMID 25401159, 2014). "We found that normalized BSHG was significantly higher in the E0771 tumor peripheries of MMP13 KO versus WT mice, suggesting different collagen I microstructure between these two groups." (PMID 24010522, 2013). "This is supported by the literature observation that MMP13 can be a critical mediator of “early stage” tumor events." (PMID 24010522, 2013). "Of these overexpressed genes, 5 (CXCR4, CXCL12, MMP2, MMP9 and MMP13) were selected on the basis of their strong correlation with tumor metastasis and were validated by qPCR." (PMID 24179538, 2013). "We found this FSHG/BSHG ratio was significantly decreased in the E0771 tumor peripheries of MMP13 KO versus WT mice." (PMID 24010522, 2013). "To investigate the levels of collagenase in mice skin, we examined the expression of MMP-13, a rodent interstitial collagenase, using Western blotting of tumour cell lysates." (PMID 23551430, 2013). "MMP13 was shown to promote angiogenesis, which is consistent with the finding in this study of down-regulated MMP13 expression and impaired tumor growth and angiogenesis in tumors on annexin A1 knockout mice." (PMID 23077482, 2012).
tumor (continued). "Since we observed inhibition of primary tumor growth and osteolytic lesions with Cmpd-1 treatment in mouse models, we further examined MMP13 localization in clinical samples." (PMID 22253746, 2012). "MMP-12 is involved in the breakdown of extracellular matrix and tissue remodeling, while MMP-13 is involved in the breakdown of extracellular matrix-collagen type II, which is important in tumor invasion and metastasis." (PMID 22815700, 2012). "Prominent MMP13 staining in the tumor vasculature of IDC and in the mouse tumors of the present study warrants further assessment." (PMID 22253746, 2012). "The human bone metastases samples revealed positive MMP13 staining by the tumor cells and osteoblasts cells while multinucleated (blue) TRAcP positive osteoclasts (green) appeared largely negative." (PMID 22253746, 2012). "This is in agreement with the literature reporting osteoblastic or periosteoclastic origins of MMP13 expression in mice, and its' involvement in bone collagenolysis during tumor-induced osteolysis." (PMID 22253746, 2012). "Primary tumors showed immunoreactivity of MMP13 in the tumor cells and surrounding stroma/extracellular matrix." (PMID 22253746, 2012). "Among MMPs, the principal player is MMP-9 secreted by monocytes and OCs with MMP-13 derived from tumour cells acting as modulator in some specific steps of the differentiation process." (PMID 22032644, 2011). "Accordingly, MMP-13 abrogation in tumour cells injected into the femurs of nude mice reduced the differentiation of TRAP positive cells in bone marrow and within the tumour mass as well as bone erosion." (PMID 22032644, 2011). "To determine if MMP-13 expressed by tumour cells and the increased OC differentiation and activation were causally linked, we used two approaches to abolish MMP-13 expression." (PMID 22032644, 2011). "We then examined the possible involvement of endostatin, which is a digestion product of type XVIII collagen by MMPs including MMP-13 and is known to inhibit angiogenesis and migration of tumour cells." (PMID 22015555, 2011). "The selective expression of MMP-13 by stromal fibroblasts neighbouring tumour islands is also reported in skin tumours developed in the human papillomavirus type 8 transgenic mouse." (PMID 22015555, 2011). "On the contrary, the CT analysis confirmed the role of MMP-13 produced by tumour cells in osteolysis." (PMID 22032644, 2011). "Previous work in our lab has shown that the stromal cells respond to the cytokine-rich environment of the tumor with altered expression of MMPs, predominantly with very high levels of MMP-13." (PMID 21461405, 2011). "It has been previously reported that up-regulation of MMP-13 in mouse bone lesions is important for regulation of tumour-induced osteolysis." (PMID 22032644, 2011). "MMP-13 is expressed predominantly by tumour cells in squamous cell carcinomas of the head, neck and vulva and in cutaneous basal cell carcinomas." (PMID 22015555, 2011). "Gene expression profiles revealed that MMP-13 was among the up-regulated genes in tumour-bone interface and its abrogation reduced bone erosion." (PMID 22032644, 2011). "The surge of MMP-13 expression in GCT stromal cells is induced by cytokines secreted by the multinucleated giant cells in the tumor environment." (PMID 21461405, 2011). "Although MMP-13 is overexpressed in a variety of malignant tumour tissues, the distribution of MMP-13 within tumours, that is, the expression by tumour cells and/or stromal cells, appears to be dependent on the tumour type." (PMID 22015555, 2011). "For MMP-13 a weak to moderate staining of the cytoplasm and nuclei of tumor cells and, in addition of the cytoplasm of normal breast cells was found." (PMID 19531263, 2009). "Similar to the findings of Zhang and colleagues, we identified MMP-13 protein to be predominately expressed in the cytoplasm of tumor cells." (PMID 19531263, 2009).